THY1 (Thy-1 cell surface antigen)
Diseases named in the same sentence as THY1 in open-access papers (continued):
Sharing a sentence is not in itself a finding about the gene and the disease.
Arthritis (14 papers, 2004 to 2024). Inflammation of a joint. "By combining transcriptomic and glycomic analysis, we report that the transformation of SFs into pro-inflammatory cells in experimental arthritis is associated with glycan remodeling, which involves the reduction of terminal sialylation in Thy1(CD90)+ sub-lining SFs upon TNF stimulation." (PMID 33879788, 2021). "Concomitantly with the shrinkage of the stably present SLSFs, we observed the emergence of arthritis-specific Thy1+ SF subpopulations (Dkk3/Lrrc15+ and Birc5/Aqp1+), accompanied by expansion of Prg4high/Thy1-LSFs." (PMID 35879783, 2022). "In a murine model of arthritis, specific depletion of FAPα+THY1+ FLS led to inflammation decrease, whereas depletion of THY1− FLS resulted in bone protection, suggesting that these cell subtypes are putative therapeutic targets." (PMID 31618926, 2019). "In line with this, a recent elegant study analyzing the inflammatory memory of SFs as a possible mechanism to explain flares in RA, identified arthritis-“primed” SLSFs (Thy1+) functioning in a mixed inflammatory/destructive mode upon arthritogenic restimulation." (PMID 35879783, 2022). "In addition, adoptive transfer of lymphoid cells together with antibody in the T cell-depleted mice was shown to induce arthritis, and the effector cells were identified as Thy-1+ and L3T4+Lyt-2-." (PMID 15535832, 2004). "Modern cellular phenotyping has uncovered that a Thy1+CD34+ subset of SFs, which expresses several complement proteins intracellularly and is found in the sublining regions of the synovium, critically contributes to arthritis pathogenicity." (PMID 34068191, 2021). "Single-cell transcriptomics in the synovium of serum transfer-induced arthritis (STIA) mice revealed two anatomically distinct fibroblast activation protein-α (FAPα)+ subpopulations, differentiated by the expression of thymus cell antigen 1 (THY1, also known as CD90)." (PMID 39906351, 2024). "Also, the arthritis occurs regardless of Thy1 status, as we have identified AR and NAR IIJ mice that are Thy1.1+Thy1.2-, Thy1.1-Thy1.2+ and Thy1.1+Thy1.2+ (data not shown)." (PMID 21749708, 2011).
colitis (13 papers, 2008 to 2026). Inflammation of the colon. "Mechanism research showed that THY1 promotes the pathological process of DSS-induced colitis through inhibiting M2 macrophage polarization." (PMID 42228713, 2026). "In the colitis model, IL-11+ fibroblasts exclusively expressed stromal cell markers, such as Thy1 and podoplanin." (PMID 33863879, 2021). "This is in line with previous work showing that both anti-CD90 (Thy-1) depletion in Rag1-deficient mice or use of Rag1.Rorc-double deficient mice, which principally lack IL-23R+ innate lymphoid cells, are similarly resistant to anti-CD40-induced colitis." (PMID 24586521, 2014). "Silencing of the THY1 significantly reversed the inflammatory response, oxidative stress level, and angiogenic activity in DSS-induced colitis, whereas overexpression of THY1 further exacerbating the reactions related to inflammation, oxidative stress, and angiogenesis." (PMID 42228713, 2026). "ILC depletion strategies, using anti-Thy1 or anti-CD90 monoclonal antibodies, have been successful in two different experimental models of IBD, Helicobacter hepaticus-induced intestinal inflammation and T-bet−/−Rag2−/− (TRUC) mice that develop spontaneous colitis, respectively." (PMID 27578924, 2016). "Thus, TNBS colitis was characterized by an absence of significant changes in markers of T cells (Thy1, Tcrb, Tcrg, Zap70, Lck), B cells (Ptprc -B220-, Ms4a1 -Cd20-, Cd22, Cd79b) and NK cells (Baat, Ncam1 -Cd56-, B3gat1 -Cd57-)." (PMID 18928539, 2008).
leukemia (13 papers, 2013 to 2025). A malignant (clonal) hematologic disorder, involving hematopoietic stem cells and characterized by the presence of primitive or atypical myeloid or lymphoid cells in the bone marrow and the blood. "ATA B cells can decrease CD5 in middle age and increase CD11b++CD22++ in ZAP70–CD5–, generating old age leukemia/lymphoma with autoimmune disease and control Thy-1, also ZAP70+CD5+ with CD11b+CD22+." (PMID 38570827, 2024). "For example, local GJ communication regulates CD90 (Thy-1) expression by cancer cells, especially leukemia, supporting their role in the dedifferentiation of cells into a fetal stage." (PMID 29695070, 2018). "In domestic animals, some markers such as GDNF family receptor alpha-1 (GFRα-1), Promyelocytic leukaemia zinc finger (PLZF), Thy-1 Membrane Glycoprotein (THY1), and Ubiquitin C-terminal hydrolase 1 (UCHL1) have been used to enrich and identify the undifferentiated spermatogonia." (PMID 37569546, 2023).
breast tumors (12 papers, 2015 to 2025). "In a previous work, we identified CD90/Thy-1 as being highly expressed in the aggressive high malignancy grade Hs578T basal-like breast tumor cell line, pointing to this molecule as a promising breast tumor marker, which should be further investigated." (PMID 29949609, 2018). "The expression of CD90/Thy-1 is demonstrated in different cells at different locations in the body but also highly expressed in the aggressive high malignancy grade basal-like breast tumour cell line (Hs578T), pointing to this molecule as a promising breast tumour marker." (PMID 34299095, 2021). "Similarly, we also observed genes that were hypermethylated at promoter regions but expressed in breast tumors (such as HOPX and THY1)." (PMID 25706888, 2015).
nasopharyngeal carcinoma (12 papers, 2008 to 2023). A carcinoma arising from the nasopharyngeal epithelium. "We had previously shown that THY1 (CD90) is a tumor suppressor in nasopharyngeal carcinoma (NPC) and that its down-regulation and loss of expression are associated with tumor metastasis, yet the mechanism leading to such effects remains unknown." (PMID 37046850, 2023). "Thy1 overexpression suppresses cell proliferation in ovarian and nasopharyngeal cancer, however, Thy1 expression in cancer stem-cells has mostly been associated with chemoresistance and increased tumor-initiating properties." (PMID 29527515, 2018). "In contrast, Thy-1 expression is reduced in other types of cancer, such as ovarian, and nasopharyngeal cancer, suggesting that in some tumor cells, Thy-1 may also act as a tumor suppressor." (PMID 33511115, 2020). "In nasopharyngal carcinoma, THY1 is poorly expressed due to its promoter hypermethylation." (PMID 30285865, 2018). "The HOPX and THY1 are well-studied TSGs in colorectal, ovarian and nasopharyngeal cancers." (PMID 25706888, 2015).
Obesity (12 papers, 2015 to 2024). Accumulation of substantial excess body fat. "Obesity is also associated with the loss of Dock 7 protein and silence of Thy-1 expression, which results in higher bone resorption and higher levels of adipogenesis, leading to impaired bone formation." (PMID 38378872, 2024). "Thy-1–KO mice are more susceptible to HFD-induced obesity and bone loss." (PMID 36066980, 2022). "In contrast, an impact of Thy-1 deficiency on osteoclasts was only seen in late, distinct obesity." (PMID 30333974, 2018). "In the present study, we demonstrated that Thy-1 deficiency augmented obesity-mediated bone loss." (PMID 30333974, 2018). "Thus, Thy-1 deficiency impaired osteoblast differentiation and activity under both lean body composition and in the early and late phase of obesity." (PMID 30333974, 2018). "Thy-1 has previously been shown to modulate adipogenesis, and Thy-1–KO mice fed a high-fat diet (HFD) develop increased obesity and bone loss." (PMID 36066980, 2022). "Since diet-induced obesity alters bone remodeling leading to decreased femoral trabecular bone mass in mice, we investigated the impact of Thy-1 on the disturbed bone remodeling in obesity." (PMID 30333974, 2018). "Thy-1-mediated effects on cortical bone therefore seem to be compensated by as yet unknown mechanisms in obesity." (PMID 30333974, 2018). "In the present study, we analyzed the impact of Thy-1 on disturbed bone metabolism in obesity." (PMID 30333974, 2018). "Thy-1-deficient (Thy-1−/−) and wildtype (WT) mice were fed with a HFD to induce obesity." (PMID 30333974, 2018). "On the whole, THBS1 facilitates obesity-associated expansion of the diaphragm FAP pool, inducing a fibrogenic transcriptomic signature typified by TGF-β–dependent gene expression and enrichment of a THY1+ subpopulation previously linked to tissue-level remodeling." (PMID 38954467, 2024). "For THY1 membrane glycoprotein (10-fold upregulated in our study), it was shown that overexpression decreases the activity of PPARγ and blocks adipocyte formation and it could therefore become a therapeutic target in obesity." (PMID 31083566, 2019). "However, obesity seems to overwrite these Thy-1-mediated effects on the Wnt pathway." (PMID 30333974, 2018). "In summary, in obesity, lack of Thy-1 resulted in reduced bone mass while bone stiffness was not affected." (PMID 30333974, 2018). "In summary, our findings show that lack of Thy-1 promotes obesity under HFD conditions while concurrently decreasing bone mass and formation." (PMID 30333974, 2018). "Recently, Thy-1 (CD90) was identified as positive regulator of osteoblast differentiation and activation, thus, promoting bone formation while concurrently inhibiting adipogenesis and obesity in mice." (PMID 30333974, 2018). "Recently, Thy-1 (CD90) was identified as a critical molecule for the differentiation of osteoblasts and, thus, promoting osteogenesis and bone formation while inhibiting adipogenesis and obesity." (PMID 30333974, 2018). "Since the hypothalamus of Thy1-Cre mice is not targeted by Cre activity, these mice do not display obesity." (PMID 29973867, 2018).
pancreatic cancer (12 papers, 2011 to 2025). "Overall, our strategy facilitates the expression and purification of Thy1-scFv while introducing its ability for diagnostic molecular imaging of pancreatic cancer." (PMID 34845270, 2021). "The purpose of this study was to engineer a production model for recombinant protein in their native form through the example of Thy1-scFv, while introducing its potential for early diagnosis of pancreatic cancer." (PMID 34845270, 2021). "miRNA-143-5p has been implicated in the pathophysiology of cancer (including colon and pancreatic cancers) and schizophrenia-related disorders, and its effects on various target genes, such as EMC2, VWC2L, THY1, SGCZ, HIF1, and JDP2, among others, have been described." (PMID 37179125, 2023).
osteoarthritis (11 papers, 2012 to 2024). A noninflammatory degenerative joint disease occurring chiefly in older persons, characterized by degeneration of the articular cartilage, hypertrophy of bone at the margins and changes in the synovial membrane. "In this regard, it is worth mentioning that a previous work noticed an expansion of a fibroblast population expressing podoplanin, CD90/Thy1 and cadherin‐11, but lacking CD34, in patients with RA relative to patients with osteoarthritis." (PMID 33350073, 2021).
Anxiety (10 papers, 2014 to 2025). Intense feelings of nervousness, tension, or panic often arise in response to interpersonal stresses. "In Thy1-aSyn mice the anxiety phenotype is developed prior to overt dopamine loss at 14 months of age and does therefore not reflect anxiety under dopamine depletion." (PMID 37349373, 2023). "The anxiety and fear deficits appear to be associated with decreased numbers of Thy1-enriched neurons in the basolateral amygdala (BLA)." (PMID 24478749, 2014). "Although the precise brain damage responsible for the deficits we saw remains to be established, our data suggest that the fear and anxiety deficits, at least, may be related to dysfunction or loss of Thy1-enriched neurons of the BLA." (PMID 24478749, 2014). "While there are some studies that report increased anxiety in A53T models, the decreased anxiety phenotype appears prominent in A53T transgenic mice yet incongruous with typical clinical symptoms, while Thy1-αSyn mice show a phenotype consistent with increased anxiety in PD." (PMID 37349373, 2023). "Second, Thy1-aSYN mice exhibit increased anxiety, that is frequently experienced by PD patients." (PMID 30333721, 2018). "For instance, BAC mice overexpressing human G2019S LRRK2 showed faster walking speed (and anxiety-like behavior) in the open field whereas human G2019S overexpressors under the Thy1 or the TetO CaMKII promoters showed transient improvement in rotarod performance or increased exploratory behavior." (PMID 25107341, 2014). "Regardless of the exact scenario, however, the reported link of Thy1+ pyramidal neurons in BLA to fear suppression suggests their damage may contribute to the heightened anxiety and/or fearfulness we observed in mice subjected to 50–60 psi blast." (PMID 24478749, 2014). "Thy1-aSyn mice develop alpha-synuclein pathology and microgliosis in the BLA and the CA1 region of the hippocampus, and increased anxiety and fear." (PMID 41274882, 2025). "This seems inconsistent with our findings; one possible explanation could be that stress-induced anxiety-like behavior may be mediated by Thy1- neurons rather than Thy1+ ones, or these two neuron groups work synergistically." (PMID 32362809, 2020). "Thus, in principle, neuronal loss or dysfunction of the amygdalofugal neurons of medial prefrontal cortex and/or of the Thy1-enriched BLA neurons could account for the increased fear and anxiety after TBI in our mice." (PMID 24478749, 2014). "Given that Thy1+ BLA neurons have recently been shown to suppress fear retention via a projection to medial central amygdala, abnormalities in this neuronal subpopulation may contribute to the increased anxiety and fear in mice subjected to 50–60 psi blast." (PMID 24478749, 2014).
fibrosis (10 papers, 2015 to 2025). the formation of excess fibrous connective tissue in an organ or tissue in a reparative or reactive process. "Oval cells also express MSC markers (c-kit and Thy-1 or CD90), and recent work has shown that murine MSCs can differentiate into oval cells that contribute to liver regeneration in a CCl4-induced fibrosis model." (PMID 31671842, 2019).
neuroblastoma (10 papers, 2013 to 2025). Neuroblastoma (NB) is the most common solid, extracranial childhood tumor. "In childhood cancer neuroblastoma, low/missing THY1 is associated with poor survival, and patients with low/missing THY1 expression were found to have a higher relapse rate." (PMID 37046850, 2023).
Parkinson disease (10 papers, 2015 to 2023). A progressive degenerative disorder of the central nervous system characterized by loss of dopamine producing neurons in the substantia nigra and the presence of Lewy bodies in the substantia nigra and locus coeruleus. "Transgenic (tg) mice overexpressing wild-type human α-syn under the Thy-1 promoter (L61) reproduce many Parkinson’s disease features, but the pathogenetic relevance of α-syn oligomers in this mouse model has not been studied in detail." (PMID 33639338, 2021). "The expression of α-synuclein was cell-wide, as is known to be the case when α-synuclein is pathologically over-expressed, such as in the Thy1- αSYN mouse model, or in human Parkinson’s disease patients with SNCA gene triplication." (PMID 33637689, 2021). "Daily intranasal administration of carnosine improved Parkinson's-like symptoms and reduced the accumulation of alpha-synuclein in Thy1-αSyn transgenic mice, a mouse model of Parkinson's disease." (PMID 33052927, 2020). "Taken together, our results show that the (Thy‐1)‐h[A30P] alpha‐synuclein transgenic mouse model displays early Parkinson's disease‐related symptoms with a concomitant downregulation of the dopaminergic system." (PMID 29541535, 2018). "Here we studied a mouse model of Parkinson’s disease (Thy-1 [A30P] α-synuclein transgenic mouse model) in the background of telomere shortening (Terc knockout mouse model)." (PMID 27550225, 2016). "In order to further understand the potential role of telomere shortening in Parkinson’s disease pathology we crossed the α-synuclein transgenic Parkinson mouse model Thy-1 [A30P] with the Terc knockout mice, a telomere erosion-based ageing mouse model." (PMID 27550225, 2016). "Photostimulation of only afferent fibers arriving from layer V of the motor cortex using transgenic mice expressing ChR2 under the Thy1 promoter has been shown to improve parkinsonism." (PMID 26979514, 2016). "In order to investigate the effects of ageing in the Parkinson’s disease mouse model, Thy-1 h[A30P] α–synuclein transgenic mice (αSYNtg/tg) were crossed with Terc knockout mice (Terc-/-)." (PMID 27550225, 2016). "We then investigated whether CsA treatment could exert a restorative action in a transgenic mouse model of Parkinson’s disease whereby the expression of wild-type human α-synuclein is driven by the neuronal promoter Thy-1." (PMID 26666562, 2015). "Using Thy1::ChR2 transgenic mice, in which ChR2 is abundant in afferent fibers but excluded from cell bodies, they showed that optogenetic high frequency stimulation of afferent fibers in the subthalamic nucleus robustly blocked motor symptoms that characterize Parkinson’s disease." (PMID 35350137, 2022).
amyloid (9 papers, 2012 to 2025). "These genes, Thy1, Gfap, Tyrobp, Ctsd, Cst7, C1qb, Lyz2, Ctss, Trem2, Mpeg1, Hexb, Cd68, C1qb, C1qa, Ctsz, Grn, Laptm5, B2m, C1qc, Hexa, and Serpina3n, were increased in the 7-month-old 5XFAD model in the cortex and associated with amyloid plaque image patterns." (PMID 38036733, 2023). "Additionally, GF Thy1-APPSWE/PS1L166P mice display attenuated amyloidosis and dampened neuro-inflammatory responses." (PMID 28874832, 2017). "Accordingly, we have recently shown the occurrence of an early, pro-inflammatory reaction in the hippocampus of young, three-month-old transgenic McGill-Thy1-APP mice in the absence of amyloid plaques but associated with intracellular accumulation of amyloid beta petide oligomers." (PMID 22472085, 2012). "Additionally, it is important to note that expression of the 5XFAD transgene used to generate the AD‐BXD reference panel is driven by a Thy‐1 promoter and likely does not fully recapitulate the endogenous pattern or amyloid pathology or presenilin expression in the periphery." (PMID 31381246, 2019).